TNFSF13 (TNF superfamily member 13)
Diseases named in the same sentence as TNFSF13 in open-access papers (continued):
Sharing a sentence is not in itself a finding about the gene and the disease.
cervical carcinoma (2 papers, 2013 to 2022). A carcinoma arising from either the exocervical squamous epithelium or the endocervical glandular epithelium. "For immunostimulator, SLC30A10 expression was correlated with TNFRSF25 (Spearman: ρ = 0.202, P = 0.00038), TNFSF13 (Spearman: ρ = -0.193, P = 0.000703), TNFRSF13C (Spearman: ρ = -0.209, P = 0.000245), and RAET1E (Spearman: ρ = 0.197, P = 0.000546) in cervical carcinoma." (PMID 35154468, 2022).
chronic periodontitis (2 papers, 2019 to 2020). A chronic inflammatory process that affects the tissues that surround and support the teeth. "In serum, RA subjects with moderate/severe periodontitis had significantly higher levels of APRIL (TNFSF13) (p = 0.013), sCD30 (TNFRSF8) (p = 0.048) and gp130 (sIL-6Rß) (p = 0.01) compared to patients with no/mild form of periodontitis." (PMID 31072030, 2019).
colorectal cancer (2 papers, 2009 to 2020). A primary or metastatic malignant neoplasm that affects the colon or rectum. "Data is presented for the validation of one potential novel clinical 5FU resistance candidate APRIL/TNFSF13 in an independent set of 234 patients with colorectal cancer." (PMID 20003335, 2009).
glioblastoma (2 papers, 2012 to 2021). The most malignant astrocytic tumor (WHO grade IV). "We subsequently investigated TNFSF13 expression in specific tumor anatomic structure based on Ivy Glioblastoma Atlas Project, and found high expression of TNFSF13 was enriched in hyperplastic blood vessels, leading edge and peri-necrotic zone, which play a crucial role in the development of tumors." (PMID 34712225, 2021). "We tested experimentally whether lowered intracellular pH would increase TNFSF13 mRNA levels in cultured glioblastoma cells, U-87 MG." (PMID 22545112, 2012).
influenza infection (2 papers, 2013 to 2022). "Of them, many had relevance in influenza infection such as genes responsible for virus entry (Anxa1/2, Cd14), interferon signaling (Dusp10, Tnfsf13), or prostaglandin synthesis (Ptgs1/2)." (PMID 35629310, 2022). "As our screens only identified loss of TNFSF13 or TNFSF12-TNFSF13 resulting in protection from influenza-induced cell death, this could suggest that TNFSF12 alone was not responsible for the cytotoxicity associated with influenza infection." (PMID 23949218, 2013).
non-small cell lung carcinoma (2 papers, 2021 to 2022). A group of at least three distinct histological types of lung cancer, including non-small cell squamous cell carcinoma, adenocarcinoma, and large cell carcinoma. "Studies have shown that high TNFSF13 expression in tumor cells and fibroblasts is associated with a poor prognosis of non-small cell lung cancer, and TNFSF13 also promotes the development of LAML." (PMID 36186454, 2022).
triple-negative breast carcinoma (2 papers, 2021 to 2022). An invasive breast carcinoma which is negative for expression of estrogen receptor (ER), progesterone receptor (PR), and human epidermal growth factor receptor 2 (HER2). "In triple-negative breast cancer (TNBC), the upregulated TNFSF13 is found to be correlated with a poor response to chemotherapy, suggesting that TNFSF13 could be a predictive biomarker for patients receiving chemotherapy." (PMID 34923982, 2021).
uveal melanoma (2 papers, 2021 to 2023). A melanoma derived from melanocytes of the uveal tract. "Remarkably, they have also found a positive correlation between AhR expression and immune stimulators including TMEM173 and TNF superfamily member 13 (TNFSF13) in testicular germ cell tumors as well as CD48 and TNFRSF25 in uveal melanoma." (PMID 37241719, 2023).
acute myeloid leukemia (1 paper, 2021). Acute myeloid leukemia (AML) is a group of neoplasms arising from precursor cells committed to the myeloid cell-line differentiation. "In acute myeloid leukemia (AML), TNFSF13 is considered as a positive regulator of AML-initiating cells." (PMID 34923982, 2021).
Autoimmunity (1 paper, 2022). The occurrence of an immune reaction against the organism's own cells or tissues. "The proliferation-inducing ligand TNFSF13 (tumor necrosis factor superfamily member 13), which is the ligand for TNFRSF17/BCMA, was identified as an essential gene for B-cell development, autoimmunity, and cancer." (PMID 36059650, 2022).
B cell deficiency (1 paper, 2021). A broad classification of disorders where circulating numbers of B lymphocytes are decreased or ineffective. "Heterologous IKZF mutation in B cell deficiency and autoimmunity, heterologous TNFAIP3 mutation in autoinflammation and immunodeficiency, heterologous IKBKB variant in common variable immunodeficiency, and homozygous TNFSF13 (APRIL) deficiency in plasmacyte defect were reported in the past 5 years." (PMID 33766139, 2021).
bipolar disorder (1 paper, 2012). A disorder of the brain that causes unusual shifts in mood, energy, activity levels and the ability to carry out day-to-day tasks. "The alteration in TNFSF13 gene expression showed relative disease specificity, as it was observed in the schizophrenia and not the bipolar disorder cases and showed relative brain region specificity in schizophrenia, as it was observed in the DLPFC and not in the OFC." (PMID 22545112, 2012).
colitis (1 paper, 2022). Inflammation of the colon. "Our results showed that TNFSF13 DNA methylation level was elevated in intestinal epithelial tissues of DSS-induced colitis, while the mRNA level and protein level were decreased." (PMID 35574272, 2022).
colorectal adenocarcinoma (1 paper, 2009). The most common type of colorectal carcinoma. "APRIL/TNFSF13 mRNA was significantly upregulated following 5FU based concurrent chemo-radiotherapy and in 5FU resistant colorectal adenocarcinoma cell lines but not in radiotherapy alone treated colorectal adenocarcinomas." (PMID 20003335, 2009).
colorectal tumor (1 paper, 2023). "In conclusion, this study confirmed that APRIL/TNFSF13, BAFF, and MMP-3 are overexpressed in colorectal tumor tissues and the overexpression of APRIL/TNFSF13, BAFF, and MMP-3 indicates their potential relationship with unfavorable clinicopathological features and poor prognosis of CRC." (PMID 37511338, 2023).
common variable immunodeficiency (1 paper, 2024). "In a 2020 study, whole exome sequencing was completed on primary cells and plasma in one patient with Common Variable Immunodeficiency analyzing TNFSF13 mRNA expression in vitro using flow cytometry and next-generation sequencing." (PMID 39974348, 2024).
Facial palsy (1 paper, 2025). Facial nerve palsy is a dysfunction of cranial nerve VII (the facial nerve) that results in inability to control facial muscles on the affected side with weakness of the muscles of facial expression and eye closure. "Our findings of higher serum TNFSF 13 in both BP and nipFP patients and higher CSF TNFSF 13 in nipFP patients as well as the association of CSF TNFSF13 with more severe facial palsy could be indicative of an increased inflammatory activity mediated by B and T cells." (PMID 41366113, 2025). "Patients with severe facial palsy (grades IV–VI according HB) revealed higher levels of the CSF cytokine TNFSF13, and clinical outcome after 3 months was less favorable at higher levels of the CSF cytokine Fractalkine." (PMID 41366113, 2025). "Patients with severe facial palsy revealed higher CSF TNFSF13 (p = 0.02), and clinical outcome after 3 months was less favorable at higher CSF Fractalkine (p = 0.025)." (PMID 41366113, 2025). "The analysis of the association between the severity of facial palsy according to HB (grades II–III; grades IV–VI), serum, and CSF cytokines revealed an association between more severe facial palsy and higher levels of the CSF cytokine TNFSF13 (p = 0.02)." (PMID 41366113, 2025).
Granuloma (1 paper, 2014). A compact, organized collection of mature mononuclear phagocytes, which may be but is not necessarily accompanied by accessory features such as necrosis. "Nevertheless, C. burnetii-induced granulomas were not only characterized by anti-inflammatory program; indeed, C. burnetii did induce several genes related to inflammation such as TNFSF13, CH25H, and IRF7 genes." (PMID 25566510, 2014).
interstitial lung disease (1 paper, 2024). A diverse group of lung diseases that affect the lung parenchyma. "Candidate biomarkers CXCL9, GDF15, and vWF have previously been shown to correlate with global JDM activity, and WFDC2 and TNFSF13 have been associated with interstitial lung disease in DM." (PMID 39529136, 2024).
lupus nephritis (1 paper, 2024). Glomerulonephritis in the context of systemic lupus erythematosus. "The therapeutic prospects of TNFSF13 (APRIL) inhibitor (atacicept) on autoimmune diseases such as lupus nephritis are huge as the clinical trials have proceeded to phase 3." (PMID 38659056, 2024).
Obesity (1 paper, 2021). Accumulation of substantial excess body fat. "Data indicate the anti-inflammatory role of high concentrations of sTNF-R1, sTNF-R2, sTNFRSF8, TNFSF13, and TNFSF13B in obesity." (PMID 34572446, 2021).
oligodendroglioma (1 paper, 2021). A well-differentiated (WHO grade II), diffusely infiltrating neuroglial tumor, typically located in the cerebral hemispheres. "In the high TNFSF13 expression cohort, typical genomic alterations in GBM-like amplification of chr7 and deletion of chr10 were observed; while in the low TNFSF13 expression cohort, deletion of 1p and 19q, a distinguishing genomic feature of oligodendroglioma, was exhibited more frequently." (PMID 34712225, 2021).
pan (1 paper, 2021). "Then we explored the mutation frequency of TNFSF13 in pan cancer from TCGA database based on cBioPortal, and prostate adenocarcinoma showed a relatively high mutation level with the TNFSF13 alteration frequency (4% approximately)." (PMID 34712225, 2021).
periodontal disease (1 paper, 2025). "In our study, both salivary and serum levels of APRIL/TNFSF13 were higher in RA patients with severe periodontal disease (PD stage III/IV) as compared to PD stage II." (PMID 40151315, 2025).
retinal disease (1 paper, 2011). "Furthermore, we identified three human retinal disease loci mapped in close proximity to certain down-regulated genes in the Otx2 CKO retina including Ccdc126, Tnfsf13 and Pitpnm1, suggesting that these genes are possibly responsible for these diseases." (PMID 21602925, 2011).
schizophrenia (1 paper, 2012). A major psychotic disorder characterized by abnormalities in the perception or expression of reality. "Patients with schizophrenia were 2.47 times more likely to have high TNFSF13 expression than unaffected controls." (PMID 22545112, 2012). "In schizophrenia, we confirmed and replicated significantly increased expression of TNFSF13 mRNA in the DLPFC." (PMID 22545112, 2012). "We found that the expression of TNFSF13 mRNA in the DLPFC was significantly increased in patients with schizophrenia in both the SMRI (U = 442.00, p = 0.048 one-tailed) and the NSW TRC (U = 463.00, p = 0.0125 one-tailed) collections." (PMID 22545112, 2012). "Our regression analysis results are consistent with TNFSF13 contributing to the established interneuron deficits in schizophrenia." (PMID 22545112, 2012). "While individuals in both the control and schizophrenia group could express elevated TNFSF13 mRNA, in the combined collection we noted that more patients with schizophrenia fell into the high expression range as illustrated by frequency distribution plots." (PMID 22545112, 2012). "Increased TNFSF13 expression suggests increased apoptotic signaling in our schizophrenia group." (PMID 22545112, 2012). "The robust abnormality in TNFSF13 mRNA transcript levels in the DLPFC warrants confirmation at the protein level as well as further study of factors contributing to the increased TNFSF13 expression in patients with schizophrenia." (PMID 22545112, 2012). "In order to put changes in TNFSF13 mRNA levels in the context of known schizophrenia neuropathology, we explored the relationship between levels of TNFSF13 mRNA and transcript levels of interneuron markers, somatostatin and parvalbumin, as well as spine markers, DLG4 and PPP1R9B." (PMID 22545112, 2012). "As parvalbumin mRNA levels in schizophrenia tissue have been observed to correlate positively with pH in several studies and TNFSF13 expression correlated negatively with tissue pH in the current study, this means that as tissue pH is lowered, parvalbumin mRNA decreases but TNFSF13 mRNA increases." (PMID 22545112, 2012). "We concluded that increased TNFSF13 expression may be one of several cell-death cytokine abnormalities that contribute to the observed brain pathology in schizophrenia, and while increased TNFSF13 may be associated with lower brain pH, the change is not necessarily causally related to brain pH." (PMID 22545112, 2012). "The effect size between control and schizophrenia cases for TNFSF13 in the OFC (r = 0.10) suggests that this negative finding is not simply attributable to the smaller sample size within the SMRI collection relative to that of the combined collections." (PMID 22545112, 2012). "The current study is the first to specifically report, confirm, and replicate in an independent postmortem tissue collection, an increase in mRNA transcript levels of the tumor necrosis factor receptor ligand, TNFSF13, in the DLPFC of patients with schizophrenia." (PMID 22545112, 2012). "One explanation for these inverse relationships with inhibitory and excitatory neuronal markers is that the cytokine actions rather than the apoptotic actions of TNFSF13 are mainly contributing to the observed pathology in schizophrenia." (PMID 22545112, 2012). "The increase in TNFSF13 mRNA was not evident in the OFC of patients with schizophrenia suggesting that increased TNFSF13 expression in the DLPFC may not be a non-specific consequence of severe mental illness." (PMID 22545112, 2012). "Therefore, the correlation between increased TNFSF13 expression with increased PPP1R9B that we find might reflect less stability of synaptic spines, which in the context of schizophrenia could be detrimental to spine density." (PMID 22545112, 2012).
yellow fever (1 paper, 2021). "Genes that were previously correlated with immunogenicity in human vaccine trials of influenza and yellow fever, including TNFSF13 (APRIL), were also enriched in uninfected rhesus monkeys in the NHP studies." (PMID 34533134, 2021).
tumor (23 papers, 2012 to 2025). "High expression of APRIL/TNFSF13 tumor transcripts was significantly associated with improved OS in TCGA-SKCM (HR = 0.69, 95% CI 0.52-0.93; p = 0.01) and in Moffitt Melanoma patients (HR = 0.51, 95% CI: 0.32-0.82; p = 0.006)." (PMID 37435077, 2023). "Single-cell RNh21A sequence data supported in situ expression of APRIL/TNFSF13 predominantly by tumor-associated macrophages, a finding which was consistently observed across a range of alternate solid tumor types." (PMID 37435077, 2023). "Serum protein and tumor transcript levels of APRIL/TNFSF13 are associated with improved survival outcomes." (PMID 37435077, 2023). "Taken together, these findings proved that TNFSF13 was closely associated with tumorigenesis and tumor progression." (PMID 34712225, 2021). "Subsequently, activated HSCs (α-HSCs) secrete TNFSF13, which recruits and promotes tumor progression through the TNFSF13/TNFRSF13B axis." (PMID 39979806, 2025). "APRIL/TNFSF13 expression was significantly positively correlated with tumor content of M1 macrophages (r = 0.5, p < 0.0001), myeloid DCs (r = 0.42, p < 0.0001) and negatively correlated with MDSC (r = -0.52, p < 0.0001) content." (PMID 37435077, 2023). "Previous researches have indicated the potential effect of TNFSF13 to induce immune cells apoptosis, immunosurveillance collapse, and tumor invasion." (PMID 34712225, 2021). "In AML, TNFSF13, secreted by normal myeloid cells, supports proliferation and apoptosis resistance of tumor cells." (PMID 32399572, 2020). "It is noteworthy that tumor necrosis binding pathway was dysregulated with differentially expressed genes Tnfsf13, Erap1, Tnfsf10, and Nucb2 (p < 0.05)." (PMID 31888290, 2019). "By decreasing the availability of APRIL/TNFSF13 in the tumor microenvironment, HTP might have also affected T regulatory cells’ expansion." (PMID 37509365, 2023). "Moreover, one recent study has demonstrated that TNFSF13 correlated with human triple negative carcinomas and induced tumor cell proliferation, which also confirmed the role of TNFSF13 in tumor aggressiveness." (PMID 34712225, 2021). "In general, these data indicated high TNFSF13 expression might possess recruitment function for infiltrating immune and stromal cells into tumor microenvironment." (PMID 34712225, 2021). "Afterwards an analysis in regard to tumor microenvironment ingredient suggested the positive correlation between TNFSF13 expression and diversified infiltrating immune and stromal cells, including NK cells, monocytes, TEM, MDSCs, Tregs, neutrophils, fibroblasts." (PMID 34712225, 2021). "Notably, TNFSF13 has been demonstrated to exert a vital role in lymphocyte maturation, physiological activities, and pathological activities, such as neoplasia." (PMID 34712225, 2021). "TNFSF13 expression was upregulated in the increase of tumor grades based on Xiangya cohort." (PMID 34712225, 2021). "Aberrant expression of TNFSF13 may contribute to tumor development through mechanisms such as promoting cell proliferation, inhibiting apoptosis, and influencing signaling pathways in tumor cells." (PMID 38149239, 2023). "Moreover, TNFSF13 is considered as an anti-apoptotic cytokine because its overexpression is frequently correlated with cancer progression and it protects tumour cells from apoptosis by promoting cell cycle progression and cell proliferation in many cancer types." (PMID 35524261, 2022). "Since TNFSF13 has an anti-apoptotic role, it is possible that the downregulation of the TNFSF13 protein-coding transcript by hypoxia-induced intron retention may contribute towards a tumor suppressor effect." (PMID 28642487, 2017). "TNFSF13, a member of the TNF superfamily, was reported to indicate the proliferative or survival state in tumor cells." (PMID 32310824, 2020).